CMPK1 (cytidine/uridine monophosphate kinase 1)
Description:
Catalyzes the phosphorylation of pyrimidine nucleoside monophosphates at the expense of ATP. Plays an important role in de novo pyrimidine nucleotide biosynthesis. Has preference for UMP and CMP as phosphate acceptors. Also displays broad nucleoside diphosphate kinase activity.
Synonyms: CK; CMK; CMPK; UMK; UMPK; UMP-CMPK
Tractability: Small molecule: a high-quality ligand is known. PROTAC: UniProt records ubiquitination sites on it; ubiquitination databases record sites on it; its protein half-life has been measured; a small molecule that binds it is known.
Target class: Enzyme
Gene: Protein-coding gene on chromosome 1 (47,333,790 to 47,394,866, forward strand). Ensembl gene ENSG00000162368.
Subcellular location: Nucleus; Cytoplasm
Subcellular location (Human Protein Atlas): Nucleoplasm
Pathways (Reactome):
Metabolism: Interconversion of nucleotide di- and triphosphates
Gene Ontology:
Molecular function: nucleoside diphosphate kinase activity; nucleoside monophosphate kinase activity; protein binding; UMP kinase activity; uridine kinase activity; ATP binding; CMP kinase activity; dCMP kinase activity; nucleobase-containing compound kinase activity; phosphotransferase activity, phosphate group as acceptor
Biological process: UDP biosynthetic process; CDP biosynthetic process; nucleobase-containing small molecule interconversion; pyrimidine ribonucleotide biosynthetic process; 'de novo' pyrimidine nucleobase biosynthetic process; pyrimidine nucleotide biosynthetic process; UMP biosynthetic process
Cellular component: cytoplasm; extracellular exosome; nucleoplasm; nucleus; cytosol
Genetic constraint (gnomAD): Loss-of-function variants: 6 observed, 13.13 expected, observed/expected ratio (o/e) 0.46, 90% interval 0.25 to 0.9. The upper end of that interval is the gene's LOEUF score, 0.9, which puts it in group 3 of 6, group 1 being the genes least tolerant of losing a copy. Missense variants: 149 observed, 183.32 expected, observed/expected ratio (o/e) 0.81, 90% interval 0.71 to 0.93. Synonymous variants: 87 observed, 68.5 expected, observed/expected ratio (o/e) 1.27, 90% interval 1.07 to 1.52.
Homologues: Orthologues: chimpanzee CMPK1 (99% identical), macaque CMPK1 (96% identical), macaque CMPK1 (94% identical), rabbit CMPK1 (94% identical), dog CMPK1 (93% identical), guinea pig CMPK1 (91% identical), mouse Cmpk1 (91% identical), rat Cmpk1 (88% identical), pig CMPK1 (76% identical), tropical clawed frog cmpk1 (75% identical), Drosophila melanogaster Ak1 (35% identical). Paralogues in human: AK1 (34% identical), AK5 (29% identical), AK2 (27% identical), AK4 (24% identical), AK4P3 (24% identical), AK3 (24% identical), AK8 (19% identical), AK7 (17% identical), AK9 (16% identical).
Diseases named in the same sentence as CMPK1 in open-access papers:
CMPK1 is named in the same sentence as 25 diseases in open-access papers, as found by Europe PMC text mining. Sharing a sentence is not in itself a finding about the gene and the disease. The quoted sentences say what the papers report.
non-small cell lung carcinoma (3 papers, 2020 to 2025). A group of at least three distinct histological types of lung cancer, including non-small cell squamous cell carcinoma, adenocarcinoma, and large cell carcinoma. "Similarly, circ-CMPK1 was significantly downregulated in nonsmall cell lung cancer and promoted tumor growth by increasing the expression of cyclin D1 via sponging and inhibiting miR-302 activity." (PMID 32867570, 2020).
breast carcinoma (2 papers, 2016 to 2025). "A recent study investigated the role of CMPK1 polymorphisms in gemcitabine‐based chemotherapy for HER2‐negative metastatic breast cancer patients." (PMID 40657553, 2025).
gastric cancer (2 papers, 2021 to 2023). A primary or metastatic malignant neoplasm involving the stomach. "Recent findings have shown that elevated CMPK1 expression correlates with extended survival and enhanced responsiveness to 5-FU therapy in gastric cancer." (PMID 37762371, 2023). "Conversely, the suppression of CMPK1 resulted in the subjection of gastric cancer cells to DNA damage and cell death following 5-FU treatment." (PMID 37762371, 2023). "Further analysis demonstrated that miR-130b as a key epigenetic regulator of CMPK1, and miR-130b-mediated attenuation of CMPK1 resulted in resistance of gastric cancer cells to DNA damage and cell death after treatment with 5-FU." (PMID 33816278, 2021).
triple-negative breast carcinoma (2 papers, 2016 to 2023). An invasive breast carcinoma which is negative for expression of estrogen receptor (ER), progesterone receptor (PR), and human epidermal growth factor receptor 2 (HER2). "A previous study identified and validated CMPK1 as a prognostic marker for triple-negative breast cancer by MS." (PMID 37501157, 2023). "We have previously identified UMP-CMP kinase (CMPK1) as a prognostic marker for triple negative breast cancer (TNBC) by mass spectrometry (MS)." (PMID 27558661, 2016).
viral infections (2 papers, 2020 to 2025). "CMPK1 is also the target of three FDA approved cancer drugs (Gemcitabine, Lamivudine, and Sofosbuvir) for the treatment of diseases induced by a virus infection, such as HCC caused by HBV/hepatitis C virus." (PMID 33424926, 2020).
diabetes (1 paper, 2025). "Integrated proteomic and transcriptomic analysis of liver tissue from patients with obesity and T2DM identified CMPK1 as significantly elevated compared with obese patients without diabetes." (PMID 41303351, 2025).
glioblastoma (1 paper, 2023). The most malignant astrocytic tumor (WHO grade IV). "Peptidyl arginine deiminase, type II (PADI2), and UMP-CMP kinase (CMPK1) transcripts were similar between glioblastoma and normal brain tissues." (PMID 37762371, 2023).
T-cell acute lymphoblastic leukemia (1 paper, 2019). Acute lymphoblastic leukemia of T-cell origin. "As an example, deletion of a CTCF binding site insulating the promoter of TAL1 gene from regulatory elements adjacent to the CMPK1 promoter was shown by CRISPR/Cas9 experiments to cause activation of TAL1, an oncogenic driver of T cell acute lymphoblastic leukemia." (PMID 31362752, 2019).
tumor (13 papers, 2008 to 2025). "Previous studies have shown that HMGB2 and CMPK1 are abundantly up-regulated in various malignant tumors, and are closely associated with tumor development and poor prognosis." (PMID 30699189, 2019). "Xenograft tumor model was established to evaluate the role of circ‐CMPK1/miR‐302e/cyclin D1 axis in vivo." (PMID 31863641, 2020). "Collectively, these results reveal that circ‐CMPK1 is a tumor growth promoting factor that can directly bind and inhibit miR‐302e expression." (PMID 31863641, 2020). "Analogously, the inhibitory effect of miR‐302e on tumor growth was effectively counteracted by restoration of circ‐CMPK1 or cyclin D1 expression." (PMID 31863641, 2020). "Mutations in UMP/CMPK1 responsible for CDV-resistance have been selected and characterized in HPV(+) tumor cells and, to our knowledge, it is the first time that this enzyme has been involved in resistance against an antiviral or an anticancer drug, in vitro or in vivo." (PMID 26824416, 2016). "Moreover the miR‐302e‐mediated tumor inhibition could be effectively counteracted by ectopic expression of circ‐CMPK1 or cyclin D1 both in vitro and in vivo." (PMID 31863641, 2020). "Importantly, the miR‐302e‐induced tumor suppressive effect could be effectively reversed by circ‐CMPK1 or cyclin D1 overexpression both in vitro and in vivo, implying that the ceRNA regulatory network of circ‐CMPK1/miR‐302e/cyclin D1 is objectively present and plays an important role in NSCLC." (PMID 31863641, 2020). "Both CMPK1 and ACADSB seem to be vital to tumor cell growth in HCC models with a lower survival rate." (PMID 33424926, 2020). "ST1926 treatment down-regulated a group of oncogenic proteins (SLC2A1, SLC25A6, CBX3, DEK, DDX39B) and up-regulated a group of presumably tumor-suppressing proteins (PEBP1, HspBP1); PADI2 and CMPK1, of unknown function in GBM, were also up-regulated." (PMID 37762371, 2023). "Studies of cytarabine and gemcitabine resistance mechanism have played an important role in the characterization of pyrimidine metabolism in tumor cells, but up to now, no description of resistance has been done regarding UMP/CMPK1." (PMID 26824416, 2016).
cancer (9 papers, 2016 to 2025). A tumor composed of atypical neoplastic, often pleomorphic cells that invade other tissues. "Notably, CMPK1 inhibition reduces cancer cell proliferation65while CTPS2 is implicated in DNA repair, potentially aiding the placenta in maintaining genomic stability under adverse conditions." (PMID 40825832, 2025). "Cytoplasmic CMPK1 (cCMPK1) was generally ubiquitous, as the majority of tissues (80.2%) expressed cCMPK1 in more (>) than 70% of carcinoma." (PMID 27558661, 2016). "On the other hand, nuclear CMPK1 (nCMPK1) staining showed differences in terms of quantity of stained carcinoma cells and staining intensity." (PMID 27558661, 2016). "CMPK1 is also of predictive and prognostic value in several cancers." (PMID 37762371, 2023). "Regarding pyrimidine metabolism, the upregulation of CMPK1, CMPK2, CTPS2, CAD, DHODH, and UMPS suggests a role in supporting placental growth under stress, reflecting their established functions in cancer cell proliferation." (PMID 40825832, 2025). "Cancer cells have also been shown to exhibit altered levels of other monophosphate kinases (CMPK1, GMPK) and this sometimes correlates with differences in cancer prognosis and the response to some chemotherapeutics." (PMID 29018771, 2017). "Furthermore, studies have described that localization of the CMPK1 (UMP/CMPK) in the nucleus and cytoplasm could accrue in several cancer cells which have also been identified as a prognostic marker." (PMID 37501157, 2023).
CMPK1 also shares sentences with these, for which no sentence is quoted: Nephropathy (2 papers); acute lymphoblastic leukemia (1); bladder cancer (1); chronic myeloid leukemia (1); hepatoma (1); ischemia (1); ischemic stroke (1); lung carcinoma (1); malaria (1); Obesity (1); ovarian tumors (1); pancreatic cancer (1); parasitemia (1); Stroke (1); temporal lobe epilepsy (1).